MTOR (mechanistic target of rapamycin kinase)
Diseases named in the same sentence as MTOR in open-access papers (continued):
Sharing a sentence is not in itself a finding about the gene and the disease.
liver cancer (280 papers, 2007 to 2026). An epithelial or non-epithelial malignant neoplasm that arises from the liver. "Pifithrin-μ, an HSP70 inhibitor, synergized with sorafenib in the induction of ferroptosis in mTOR-activated liver cancer cells and suppression of TSC2-deficient hepatocarcinogenesis." (PMID 39863613, 2025). "We then assessed the impact of mTOR on sorafenib resistance in human liver cancer cells by using 3 TSC2-deficient cell lines (SNU886, SNU398 and Li7) and 3 TSC2 WT cell lines (HCCLM3, HepG2 and MHCC97H)." (PMID 39863613, 2025). "Hyperactivation of PI3K/PTEN/Akt/mTOR axis is implicated in liver cancer cell proliferation and migration by activating matrix metallopeptidase 9 (MMP9)." (PMID 38965615, 2024). "Various alterations of proto-oncogenes and tumor suppressors cause malfunction of PTEN-PI3K/AKT/mTOR signaling pathway in hepatic cancer." (PMID 38459588, 2024). "To investigate the involvement of aberrant PTEN-PI3K/AKT/mTOR signaling cascade in HBV-associated liver cancer, we studied cancer development of liver-specific HBV transgenic and Pten deletion mice." (PMID 38459588, 2024). "miRNA-221 and -222, involved in the regulation of the Akt-mTOR signal transduction pathway, were both identified in our samples and had been found previously in circulating EVs of liver cancer patients where they were associated with poor prognosis." (PMID 37762298, 2023). "Similar to AKT phosphorylation, mTOR activation is also closely associated with the initiation and progression of liver cancers." (PMID 31293977, 2019). "In liver cancer with mutations in β-catenin, levels of GS, a target of β-catenin, are increased and its disruption prevents mTOR phosphorylation at Ser2448, suggesting downregulation of mTOR activity." (PMID 31817676, 2019). "Another evidence for the benefit for interference with tumor-associated angiogenesis in liver cancers is provided by data from clinical and pre-clinical studies with mTOR inhibitors such as everolimus and sirolimus." (PMID 26413215, 2015). "Additionally, numerous studies have shown that mutations in the pre-S region are associated with the formation of liver cancer through the mediating mTOR signaling pathway, which is situated within the coding region of L-HBsAg 97,102-110." (PMID 39247820, 2024). "Also in agreement with the idea is that activating mutations upstream of mTOR in Tuberous sclerosis complex (TSC) are regularly detected in liver cancer, suggesting that this pathway is indeed important for the development of liver cancer." (PMID 34650055, 2021). "Liver cancer development in different mouse models with genetic or dietary alterations is frequently preceded by hepatic steatosis and is associated with a deregulation of the mTOR pathway." (PMID 32070029, 2020). "The main reason for this result may be that Brusatol over-activates autophagy of liver cancer cells through the PI3K/AKT/mTOR pathway, thereby causing autophagic cell death (also known as programmed cell death (PCD) type II) of liver cancer cells." (PMID 31835352, 2019). "mTOR, as a central sensor for cell nutrient and growth, provides a pivotal link between environmental risk factors and the cellular damage that initiates the inflammatory and regenerative responses leading to liver cancer." (PMID 27167192, 2016). "Abnormal activation of mTOR in liver cancer can lead to chemotherapy resistance, and there exist two complexes, mTORC1 and mTORC2." (PMID 40698038, 2025). "We observed that mTOR activation results in sorafenib resistance in liver cancer cells by enhancing cellular antioxidant capacity." (PMID 39863613, 2025). "Studies have reported that TRIB3 can regulate cell metabolism via PI3K/AKT/mTOR circuit for liver cancer, oral and nasopharyngeal carcinoma." (PMID 39869954, 2025).
liver cancer (continued). "Our findings highlight the pivotal role of the mTOR-CREB1-SESN3 axis in sorafenib resistance of liver cancer and pave the way for combining pifithrin-μ and sorafenib for the treatment of mTOR-activated liver cancer." (PMID 39863613, 2025). "To confirm sorafenib resistance of mTOR-activated liver cancer cells relying on high expression of SESN3, we overexpressed SESN3 in SNU886/shmTOR cells." (PMID 39863613, 2025). "An increase in PI3K activity leads to phosphorylation of AKT, which in turn activates mTOR and promotes cell cycle progression and protein synthesis, thus promoting the development of liver cancer." (PMID 40647128, 2025). "Targeting the mTOR signaling pathway is thus expected to be an important strategy to reverse sorafenib resistance for liver cancer." (PMID 39863613, 2025). "Taken together, pifithrin-μ suppresses CREB1/CREBBP complex formation, CREB1-mediated transcription, and sorafenib resistance of mTOR-activated liver cancer cells." (PMID 39863613, 2025). "Reports indicate that the PI3K/Akt/mTOR pathway promotes liver cancer stem cell formation and drives the malignant progression of liver cancer." (PMID 41425729, 2025). "The PI3K/AKT/mTOR signaling pathway plays a key role in the occurrence and development of liver cancer." (PMID 40647128, 2025). "By modulating the PI3K/Akt/mTOR signaling pathway, Brusatol effectively inhibits proliferation, induces apoptosis, and thereby suppresses tumor invasion and migration in liver cancer." (PMID 38974037, 2024). "AgNPs have been shown to activate the AMPK/mTOR signalling pathway, leading to autophagy induction in liver cancer cells." (PMID 38575697, 2024). "AS-IV inhibits the expression of p-PI3K, p-Akt, and p-mTOR, thereby inhibiting the proliferation of lung and liver cancer cells through the PI3K/Akt/mTOR signaling pathway." (PMID 39064966, 2024). "Since the PI3K/AKT/mTOR pathway is activated in HCC, activated mTOR serves as a representative marker for detecting the recovery or recurrence of liver cancer, including cholangiocarcinoma and hepatoblastoma." (PMID 39349424, 2024). "Regarding the anti-cancer effect of Aln, recent investigations have unveiled its effect on suppressing liver cancer cell line proliferation by modulating the PI3K/Akt/mTOR signaling pathway." (PMID 39519569, 2024). "This activation of the AMPK/mTOR pathway by AgNPs promotes the degradation of damaged proteins and organelles, ultimately leading to cell death in liver cancer cells." (PMID 38575697, 2024). "In some cases, these viral proteins can affect the normal physiological activities of liver cells, resulting in ER stress, activating mTOR, and ultimately leading to the progression of liver-related diseases such as cirrhosis and liver cancer." (PMID 39247820, 2024). "The accumulation of oleic acid (OA) and PA promotes liver cancer by suppressing Pten, an inhibitor of Pi3k/Akt/mammalian target of rapamycin (mTOR) signaling." (PMID 38846491, 2024). "A ruthenium(III)-pyrimidine Schiff base complex induced apoptotic cell death in liver cancer HepG2 cells along with downregulation of the transcripts of the mTOR/Akt and NF-κB genes." (PMID 38104089, 2023). "Aberrantly activation of the key signaling pathway Akt/mTOR in liver cancer contributes to the deregulation of the cell cycle, proliferation, cell death, and inflammation." (PMID 36980792, 2023). "Very recently it has been reported that 16F16, a PDIA3 inhibitor, enhances the antiproliferative effect of the mTOR inhibitor everolimus in liver cancer." (PMID 36769334, 2023). "The study team demonstrated that temsirolimus suppresses the activity of mTOR and its downstream components, which has inhibitory effects on Bel-7402 liver cancer cells." (PMID 36826066, 2023). "Previous studies have shown a pivotal role of the mTOR signalling cascade in primary liver cancer, including CCA, where upon hyper activation, mTOR signalling promotes cell proliferation contributing to tumour progression." (PMID 37841311, 2023).
liver cancer (continued). "Taken together, these results indicate that FBXL6 activates the oncogenic KRAS/MEK/ERK axis, promoting mTOR signaling activation, which leads to the carcinogenesis and development of liver cancer." (PMID 38124228, 2023). "Of interest, E2F1 has been reported to function as a critical antiapoptotic factor in human and rodent liver cancer via activation of the protein kinase B (AKT)/mammalian target of rapamycin (mTOR) signaling pathway." (PMID 36777627, 2023). "In a groundbreaking revelation, this study demonstrates, for the very first time, that vine pear root induces cell apoptosis and autophagy in liver cancer cells by inhibiting the AKT/mTOR signaling pathway." (PMID 38027882, 2023). "It has been reported that liver cancer is often driven by the activation of AKT/mTOR signaling and that glycolysis activity is increased during HCC growth." (PMID 36768977, 2023). "IQGAP1 is a scaffold protein which facilitates the interaction of mTOR and Akt and thus promotes liver cancer progression." (PMID 37202772, 2023). "In conclusion, cuproptosis-related lncRNAs can promote the aggressiveness and antiapoptotic abilities of liver cancer cells through the PI3K/AKT/mTOR pathway, thus affecting liver cancer tumor progression." (PMID 36597032, 2023). "Taken together, they provide evidence that prunetrin has an anti-cancerous ability in Hep3B liver cancer cells by arresting the cell cycle via p38 and inhibiting mTOR/AKT." (PMID 37571343, 2023). "The lncRNA SFTA1P acts as an oncogene and promotes the growth and invasion of lung and liver cancers in various signaling pathways, such as mTOR signaling pathway, AKT signaling pathway." (PMID 36819091, 2023). "Quercetin has been found to reduce HK2 levels and inhibit the AKT/mTOR pathway in liver cancer cells in vivo and in vitro." (PMID 37663261, 2023). "In this work, we found that liver cancer cells cultured in pH 6.5 medium increased PI3K/AKT/mTOR activity, and expression of ASIC1α modulates the activity of this pathway." (PMID 35840921, 2022). "We conclude that ASIC1α can regulate migration, invasion, and proliferation of liver cancer cells through the MMP-2/9/PI3K/AKT/mTOR pathway." (PMID 35840921, 2022). "PESV Smp43 can regulate the PI3K/AKT/mTOR pathway by inducing autophagy in liver cancer cells to exert an anti-tumor effect." (PMID 35847007, 2022). "The infiltrating NK cells from patients with liver cancer were reverted by inhibiting the mTOR/drp1 pathway, suggesting a novel therapeutic approach using mTOR inhibitors for NK cells in solid tumors." (PMID 35769460, 2022). "In the regulatory network constructed in the present study, lncRNA SFTA1P has been reported to downregulate miR-4766-5p through the PI3K/AKT/mTOR signaling pathway to promote liver cancer growth." (PMID 35155682, 2022). "Growth inhibition by a mTOR inhibitor sirolimus on 20 liver cancer cell lines was strongly correlated with mTOR pathway activity." (PMID 36309506, 2022). "For example, CXC195, a tetramethylpyrazine with antioxidant activity, triggers apoptosis in liver cancer cells by suppressing the PI3K/AKT/mTOR pathway." (PMID 36139919, 2022). "Kaempferol regulates PI3K/ mammalian target of rapamycin (mTOR)/MMPs protein pathways in liver cancers." (PMID 36184634, 2022). "In this study, we examine the roles of several mTOR-regulated GTPases in senescence-like liver cancer cells and the mechanisms in drug resistance." (PMID 36267578, 2022). "In a previous study, isoquercitrin showed a tendency to induce apoptosis and autophagy by inhibiting the downstream factor p70S6K through the inhibition of mTOR in liver cancer cells." (PMID 35884773, 2022).
liver cancer (continued). "To test if mTOR activity predicts the response to pathway inhibitors, we explored public data of proteome and drug screening on liver cancer cell lines." (PMID 36309506, 2022). "Anti-mTOR ChIP assay detected strong mTOR binding to the promoter region of NEAT1 promoter in a rapamycin-sensitive manner in human liver cancer cells." (PMID 35547764, 2022). "The results of molecular docking predicted that several key targets of liver cancer (along with MTOR, EGFR, MAPK3, and PIK3R1) bind stably with the corresponding active ingredient of F. indica." (PMID 35745580, 2022). "In our case, SMC treatment reprogrammed liver cancer cells’ metabolic pattern through modulating the PI3K/Akt/mTOR axis." (PMID 35343115, 2022). "Targeted therapy for the PI3K/AKT/mTOR signalling pathway provides important treatment opportunities for patients with liver cancer." (PMID 35165269, 2022). "Patulin, a Penicillium-derived compound, promotes ROS generation and autophagy of liver cancer cells by inactivating AKT1/mTOR, reverted by N-acetylcysteine." (PMID 36139919, 2022). "This demonstrates conclusively that the dysregulation of mTOR is emphasized in the pathogenesis of liver cancer." (PMID 35745580, 2022). "The results indicated that ASIC1α can up-regulate the expression of MMP-2/9 to enhance the migration, invasion, and proliferation of liver cancer cells via the PI3K/AKT/mTOR pathway." (PMID 35840921, 2022). "4-Hydroxyderricin, an Angelica keiskei Koidzumi-derived natural product, induced G1 or G2/M arrest for liver cancer cells (HepG2 and Huh7 cells) by down-regulating mTOR." (PMID 36139919, 2022). "The combination of aloin and metformin was found to inhibit the growth and invasion of liver cancer through the PI3K/AKT/mTOR pathway and induce apoptosis and autophagy, thereby exerting anti-tumor effects." (PMID 35602603, 2022). "We further demonstrated that ASIC1α up-regulates MMP-2/9 via activation of the PI3K/AKT/mTOR pathway, thereby promoting migration, invasion, and proliferation of liver cancer cells." (PMID 35840921, 2022). "It is important to note that two of our major targets, MTOR and MAPK3, are primarily implicated in liver cancer resistance pathways." (PMID 35745580, 2022). "Increased mTOR signaling often occurs in liver cancer and is involved in drug resistance, which is why it has been proposed to be suitable for drug targeting approaches." (PMID 35453756, 2022). "ZZXJD induced autophagy and apoptosis of liver cancer cells via inhibiting AKT/mTOR signaling pathway and JAK2/STAT3 signaling pathway, thereby affecting the growth and survival of liver cancer cells." (PMID 35432564, 2022). "In particular, MYO18B is related to PI3K/AKT/mTOR, a liver cancer-related pathway, and showed a positive correlation with the increase in methylation as the FLI increased over time." (PMID 35723298, 2022). "Several studies have shown that lncRNAs also regulate other mTOR signaling pathways in liver cancer." (PMID 34123955, 2021). "INH-mediated histone Kinic upregulates PIK3R1 gene expression and activates the PI3K/Akt/mTOR signalling pathway in liver cancer cells, linking INH to tumourigenicity in the liver." (PMID 34545082, 2021). "To date, there have been no reports on the role of histone methylation and acetylation in liver cancer through the mTOR signaling pathway." (PMID 34123955, 2021). "Zhou and his team discovered SMARCD1, a subunit of the SWI/SNF complex, as a promising prognostic predictor that promotes liver cancer growth through the mTOR pathway." (PMID 34123955, 2021). "We analyzed the expressions of CDK4/6 and PI3K/AKT/mTOR in normal human tissues and liver cancer patient tissues through ualcan." (PMID 34335258, 2021). "Another study demonstrated PI3K-Akt-mTOR activation in DEHP-exposed liver cancer cell proliferation." (PMID 34208283, 2021). "Of note, GCDCA has been reported to promote invasion and migration of liver cancer through AMPK/mTOR-dependent autophagy activation." (PMID 34759281, 2021).
liver cancer (continued). "It further shows that inhibiting or interfering with mTOR-related molecules can reverse the promotion effect of SSd on radiation-induced apoptosis of liver cancer cells." (PMID 33628104, 2021). "There is growing evidence that the mTOR signaling pathway plays an important role in the occurrence and development of many malignant cancers, including lung, breast, stomach, and liver cancer." (PMID 34093717, 2021). "Silencing of lncRNA HEIH inhibits liver cancer cell growth and metastasis through miR-199a-3p/mTOR axis." (PMID 33899079, 2021). "In conclusion, MET acted as a “gate-keeper” for suppressing liver cancer immunogenicity by regulating the lysosomal V-ATPase–mTOR complex." (PMID 32764535, 2020). "The kinase mTOR is a master regulator of cellular metabolism and growth, and increased mTOR activity promotes liver cancer development in mice." (PMID 32231246, 2020). "Here, we have found the hepatocyte growth factor (HGF) receptor (MET) is required for mTOR activation-stimulated mitochondrial oxidative phosphorylation (OXPHOS) in a phosphorylation-dependent manner in liver cancer." (PMID 33377662, 2020). "In this study, we found that RAB9A activated the AKT/mTOR signaling pathway in human liver cancer cells." (PMID 32420351, 2020). "We also demonstrate that the newly discovered MET–V-ATPase–MTOR signaling pathway more strongly suppresses liver cancer immunogenicity than does the traditional MET–AKT–MTOR pathway." (PMID 32764535, 2020). "The efficacy of chemotherapy-based liver cancer vaccination was markedly enhanced by targeting the MET–V-ATPase–MTOR axis, highlighting a translational strategy for identifying MET-associated drug candidates for cancer prevention." (PMID 32764535, 2020). "mTOR signaling is excessive activated in tumor NK cells from patients with liver cancer, but is inhibited in peripheral blood NK cells from patients with metastatic breast cancer, and such aberrant mTOR activity is a critical driver of NK cell dysfunction." (PMID 32983138, 2020). "The activation of the PI3K/Akt/mTOR signaling pathway is a crucial event in the progression of human liver cancer." (PMID 30959969, 2019). "In summary, the important role of AMPK/mTOR-mediated autophagy in the treatment of liver cancer has been reported." (PMID 31835352, 2019). "The expression of STAT3 can be reduced by mTOR blocking, which is closely related to the invasion and metastasis of liver cancer cells." (PMID 31696055, 2019). "In fact, very recently, the same group that initially proposed the mutual link between ASCT2 expression and the mTOR pathway likewise reported that mTOR signaling is unaffected in epithelial and mesenchymal human liver cancer cell ASCT2 knockout cells." (PMID 30234109, 2018). "In conclusion, our results demonstrate that H2S is involved in liver cancer and that its effects are mediated through thePI3K/Akt/mTOR signaling pathway." (PMID 28333142, 2017). "In the cancer studies, miR-137 was found to exert its anti-tumor activity via inhibiting the AKT2/mTOR signaling pathway in the liver cancer." (PMID 29016699, 2017). "mTOR pathway is a major survival signal, which plays a pivotal role in cell growth and metabolism and is up-regulated in almost 50% of liver cancer." (PMID 27808117, 2016). "NF-κB, Akt, MAPK and mTOR are the most prevalent survival signals promoting the progression of hepatic cancer and most of the drugs targeting this cancer are inhibitors of these pathways." (PMID 27808117, 2016). "Inducing mitochondrial apoptosis in liver cancer cells and activating autophagic cell death in liver cancer cells by activation of Beclin-1 and suppressing the mTOR-signaling pathway." (PMID 26633388, 2015). "This further suggests that BCAAs and glutamic acid can be considered candidate biomarkers for liver cancer since they are known to activate Akt-driven mTOR pathway." (PMID 26030804, 2015).